MMP2 (matrix metallopeptidase 2)
Diseases named in the same sentence as MMP2 in open-access papers (continued):
Sharing a sentence is not in itself a finding about the gene and the disease.
cancer (continued). "These exosomes activate the NF-κB, ERK, and c-FLIPL signaling pathways through the Fas/FasL-dependent trail, leading to MMP2, MMP9, and COX2 increased expression in B16 cancer cells, which play a critical role in cancer cell metastasis." (PMID 35550636, 2022). "Secretion of MMP-2 and MMP-9 was shown to break down the basement membrane and promote lymph node invasion and cancer metastasis, thus leading to poor prognoses." (PMID 36226250, 2022). "MMP2 and MMP9 expression in metastatic cancer cells is often elevated and they are considered of particular importance in developing metastatic potential, particularly in tissues where ECM is abundant in collagen type IV." (PMID 36143328, 2022). "We found that cancer cells strongly express LSR and MMP2 in invasive lesions deep in the myometrium." (PMID 35729527, 2022). "As detected by in-gel zymography, ectopic MCT-1 expression promoted higher MMP-9 and MMP-2 activities than control cells, and shMnSOD effectively decreased MMP-2 but only modestly reduced MMP-9 in cancer cells compared with the scramble control." (PMID 35017469, 2022). "Reportedly, the extracts of the fruit, stems, seeds, and twigs of A.muricata administered to fibrosarcoma cells (HT1080) inhibited matrix metalloproteinases (MMPs) such as MMP-2 and MMP-9, which play important roles in cancer progression." (PMID 35208993, 2022). "Thereby, MMP2 and MMP9 can stimulate cell proliferation and angiogenesis and have been attributed a role in early-stage tumorigenesis and cancer progression." (PMID 36013233, 2022). "All experimental niosome groups had downregulatedexpression levelsof Bcl2, Drp1, MMP-2, and MMP-9 in both the 4T1 and SKBR3 cancer cellscompared to the control (p < 0.001)." (PMID 35129960, 2022). "MMPS is zinc-dependent endopeptidases that degrade essentially all extracellular matrix components, with MMP-2 and MMP-9 playing a role in the migration and invasion of cancer." (PMID 36276736, 2022). "Among MMPs, MMP-1, MMP-2, and MMP-9 are reported to be most commonly related to malignant tumors, their metastases, and local invasion." (PMID 36551933, 2022). "The action of TIMP-1 is achieved via reduction of collagen-degrading enzymes, MMP-2 and MMP-9, that promote cancer cell invasiveness." (PMID 36291926, 2022). "N-terminally located EGF repeats present in LAMC2 are cleaved by MMP-2 or MT1-MMP and activate EGFR and the MAPK pathway to foster migration and survival of cancer cells." (PMID 36076232, 2022). "In contrast, when NF-κB translocation and transcriptional activity are inhibited, the expression of MMP2 and MMP9 is reduced and the expression of TIMP-2 is increased, further inhibiting the migration of cancer cells." (PMID 35770085, 2022). "Our results highlight the relevance of the MMP2/9 pathway in the development of PC in patients with CRC and suggest a possible therapeutic window in which to prevent PC at the stage of cancer cell invasion." (PMID 35954423, 2022). "The expression of MMP2 is regulated by the ID2 and ID2 promotes cell migration and invasion in different types of human cancer cells." (PMID 35705978, 2022). "Nevertheless, MMPs, especially the gelatinases MMP-2 and MMP-9, have a significant role in the development and progression of cancers, including those of the colon, lung, prostate, and breast." (PMID 35457074, 2022). "MMP-2, MMP-7, MMP-9, TIMP-1, and TIMP-2 research has received considerable attention since they play a number of roles in cancer." (PMID 36250005, 2022). "MMP2 and MMP9 are two special subtypes of MMPs, which have been deeply studied in cancer metastasis in recent years." (PMID 35178453, 2022).
cancer (continued). "NETs induce gene expression of cancer stem cell marker CD24, and proinflammatory factors, such as IL1β, IL6, IL8, CXC motif chemokine receptor 1 (CXCR1), MMP2, MMP9 in cocultured luminal breast cancer cells." (PMID 35574410, 2022). "A recent study sought to establish a link between MMP-2, MMP-7, and their inhibitor, TIMP-2, in adult and pediatric cancer." (PMID 36250005, 2022). "The membrane protein TMEM240 also negatively regulated several extracellular and membrane proteins involved in cell proliferation, migration, and cancer EMT, such as SDF-1, FGF2, oncostatin M, and MMP2." (PMID 35715741, 2022). "Both MMP2 and MMP9 are extensively studied for cancer metastasis in a large variety of experimental as well as clinical cancer models, therefore, inhibiting, MMPs is suggested to combat cancer." (PMID 32761892, 2022). "As the main family members of MMPs, MMP2 and MMP9 play an important role in the invasion and metastasis of cancer cells." (PMID 35468097, 2022). "In this study, exosomal HSPC111 derived from CRC cells induces a panel of cancer-promoting factors in CAFs, including CXCL5, TGF-β, MMP2 and SERPINE1, so as to enhance their cancer-promoting effects." (PMID 35027547, 2022). "Overproduction of inflammatory cytokines, fibrotic proteins such as MMP-2 and MMP-9 expressions, and excess extracellular matrix deposition result in fibrosis, which aids in cancer progression." (PMID 36143462, 2022). "Numerous studies have reported that MMP-1, MMP-2, and MMP-9 enzymes and TIMP-1 and TIMP-2 inhibitors play an active role in angiogenesis, local invasiveness, and metastatic potential of malignant tumors." (PMID 36551933, 2022). "MMP2 and MMP9 were EMT-related genes which were closely related to the invasion or metastasis of cancer." (PMID 35043728, 2022). "This suggests that the upstream regulators of ECM molecules, such as MMP2 and MMP9, and inhibition of EMT can potentially reduce AMPK expression in cancers." (PMID 35770085, 2022). "The expression of MMP2 and MMP9 in GB found that the treatment with GSK343 was able to significantly reduce their expression both in vitro and in vivo, counteracting cancer cell migration." (PMID 36430394, 2022). "The most promising derivatives regarding anticancer activity and selectivity were in vitro evaluated for their inhibitory activities against MMP-2, CA II, and VEGFR-2 which are crucial in various carcinogenesis events of the selected cancer types." (PMID 35458618, 2022). "EGCG is also effective in the inhibition of MMP-2 and MMP-9, which are responsible for degrading the basement membrane and assisting cell invasion and are commonly overexpressed in cancer." (PMID 35956766, 2022). "In the MMP family, matrix metalloproteinase-2 and matrix metalloproteinase-9 (MMP-2/9) have been considered important markers for diseases, such as inflammation, cardiovascular diseases, and cancer." (PMID 35154500, 2022). "One significant feature of these phenotype cancer cells was their high expression of mesenchymal markers, such as CDH2, S100A4, MMP2, WNT5A, and ZEB1." (PMID 36553542, 2022). "The metastasis of cancer cells depends in part on the EMT process and matrix metalloproteinases, such as Snail, MMP2 and MMP9." (PMID 35178453, 2022). "Theexpression levels of MMP-2 and MMP-9 in FPNCE were lower than those in the NCE (p <0.05); the expression levels in the NCE in both cancer cell lineswere the same and showed lower amounts compared to CIS+EPI (p < 0.01)." (PMID 35129960, 2022). "The fragment of laminin-332 γ2 chain after cleavage by MT1-MMP or MMP-2 can bind to and activate EGFR and downstream MAPK signaling in cancer cells as well as MMP-2 gene expression and cell migration." (PMID 35008401, 2022).
cancer (continued). "The MAPK pathway is a prominent mechanism for coordinating transcription factors that are activated by ERK kinase to modulate downstream MMP-2 and MMP-9 genetic expression and afterward elevate cancer onset and development." (PMID 35860597, 2022). "Crucially, TIMP-1 inhibits collagen-degrading enzymes such as matrix metalloproteinase (MMP)-2 and MMP-9, which play an important role in promoting cancer metastasis." (PMID 35277658, 2022). "Matrix metalloproteinase (MMP) family proteins, such as MMP2 and MMP9, are of vital importance in cancer metastasis, and MMPs are highly expressed in cancers." (PMID 35646704, 2022). "Although different markers were used to evaluate EMT in cancers, there was a consistent CCR7-induced increased activation of Slug, N-cadherin, TGF-β, vimentin, phospho-ERK, phospho-Akt, MMP-2, MMP-9 and Snail attenuation of E-cadherin." (PMID 35203305, 2022). "It is also involved in the degradation of ECM by the secretion of MMP-2 and MMP-9, which depicts the importance of ECM and macrophages in the progression of cancer." (PMID 35205204, 2022). "Considering the characteristics of breast molecular subtypes and hormone-positive BC expression of VEGF, research has shown that cancer progression can be arrested or slowed down by targeting TGF-β1, MMP-2, and MMP-9 when irradiated by a proton beam." (PMID 35747793, 2022). "By regulating EMT-related factors (like MMP2, MMP9 and fibronectin) and cell cycle suppressor (p21 and p27), Akt1/p-Akt1 involved in regulating cell motility and growth in various cancer cells." (PMID 35953860, 2022). "Apart from degrading ECM components, MMP-14 is also responsible for the activation of pro-MMP-2, pro-MMP-9, and pro-MMP-13, of which pro-MMP-2 and pro-MMP-9 activation have been claimed as a crucial step in cancer cell invasion and metastasis." (PMID 35586209, 2022). "The repressive result of CA on MMP-2 and MMP-9 is connected with the obstruction of NF-κB activation as verified in cancer cells induced via PMA, which reduces cancer invasiveness and growth." (PMID 35355732, 2022). "Regarding cancer metastasis, curcumin and PGV-1 showed inhibitory activities against cell migration and inhibited MMP-2 and MMP-9 protein expression." (PMID 33747866, 2021). "Cannabinoids can inhibit the invasion and metastasis of cancer cells by downregulating vascular endothelial growth factor (VEGF), matrix metalloproteinase 2 (MMP2), MMP9, and the adhesion molecule E-cadherin." (PMID 34503163, 2021). "The expression of apoptosis-, growth- and metastasis-related proteins, such as Bcl-xL, Bcl-2, VEGF, Src, CXCR4, and MMP2/9 were also regulated by phosphorylated STAT3 forms, thus promoting the growth, development and inhibition apoptosis of cancer cells." (PMID 34976809, 2021). "Possible mechanism of circLMNB1 (hsa_circ_0127801) includes upregulation of MMP-2, MMP-9, and N-cadherin expression, which are related to the primary mechanism of cancer cell invasion and metastasis, and EMT." (PMID 34298612, 2021). "EMMPRIN induces a metastatic phenotype by triggering the production of matrix metalloproteinase proteins (MMPs) such as MMP1 and MMP2, and vascular endothelial growth factor (VEGF) in cancer cells and the surrounding stromal cells." (PMID 34565336, 2021). "C5AR2 overexpression also upregulated the expression levels of MMP2 and MMP9, which were reported as oncogenes correlated with metastasis and invasion in various cancers." (PMID 34595119, 2021). "Both MMP-2 and MMP-9 contribute to various processes in cancer including invasion, metastasis, and angiogenesis." (PMID 34654351, 2021). "MMP-2 and MMP-9 are important enzymes responsible for degradation of the extracellular matrix, resulting in cancer cell migration and invasion." (PMID 33958506, 2021). "Expression levels of MMP2 and MMP14 were similar in both tissue types; MMP3 protein expression was lower in para-cancer tissues than in HCC tissues; MMP11 protein expression was higher in HCC tissues." (PMID 34376644, 2021).
cancer (continued). "We focused on proteins determining angiogenic properties (vascular endothelial growth factor, VEGF-A), migratory phenotype (vimentin, Vim) and invasive/metastatic potential (Matrix metalloproteinases, MMP-2 and MMP-9) of cancer cells." (PMID 33670389, 2021). "STAT3 activation plays an important role in metastasis, and STAT3 increases the expressions of MMP2 and MMP9, which act as key mediators of the metastatic process of cancer cells." (PMID 34876128, 2021). "For this, we searched for proteins not only with differential secretion patterns according to altered expression of MMP-2 in HCT116 CRC cells, but also showing different levels in the plasma and tissue of CRC patients relative to cancer stage." (PMID 34429501, 2021). "In previous studies, Fascin-1 is reported to regulate migration and invasion of cancer cells via upregulating matrix metalloproteinases (MMP) expression, such as MMP2 and MMP9." (PMID 34897283, 2021). "Metalloproteinases are broadly recognized as being involved in cancer cell invasion and migration; thus, we analyzed the effects of TFEB on metalloproteinases by detecting the expression level of MMP2 and MMP9." (PMID 33732651, 2021). "Activation of miR‐21 also increases the expression of MMP-2 and MMP-9, known cancer markers involved in invasion, metastasis and angiogenesis of cancer." (PMID 33863340, 2021). "In HCC, MMP-2 and MMP-9 are two main components of MMPs that play an important in cancer cell invasion and migration." (PMID 34066056, 2021). "FN1 was previously shown to be able to activate MMP2 and MMP9 expression during malignant tumor progression, facilitating cell migration, invasion, and distant metastasis." (PMID 34758823, 2021). "MMP-7 is also overexpressed in ovarian serous cancer tissues, where it increases cellular invasiveness by activating MMP-2 and -9 or by IGFBP breakdown, enhancing IGF concentration and cancer cell proliferation." (PMID 35145899, 2021). "ADAMTS9-AS1 interference enhanced cancer proliferation and invasion, facilitated levels of KI67, PCNA, MMP-9 and MMP-2, and activated the JAK STAT signaling pathway." (PMID 34900984, 2021). "Functionally, SH3PXD2B can recruit membrane type-1 matrix metalloproteinase (MT1-MMP) to the incomplete podosomes to activate MMP2 and MMP9, leading to matrix degradation and cancer cell invasion." (PMID 33906640, 2021). "The prognostic role of MMP-2, MMP-9, and MMP-14 in UM was recognized in several studies due to their crucial role in promoting cancer cell motility and angiogenesis, ultimately leading to the development of metastases." (PMID 34195299, 2021). "It has been demonstrated that MMP-2 can regulate the extracellular matrix (ECM) degradation, which plays an important role in cancer development." (PMID 34646828, 2021). "MMP2 and MMP9 can degrade type IV collagen and promote the invasion and migration of malignant tumors." (PMID 34497265, 2021). "Matrix metalloproteinase-2 (MMP2) is involved in the breakdown of ECM and has a strong correlation to the progression of metastasis in many forms of cancer." (PMID 33810045, 2021). "Both MMP2 and MMP9 are highly expressed in cancer cells, and they participate in cancer invasion, angiogenesis, and metastasis." (PMID 33923236, 2021). "Regulates cancer cells' survival, growth, and invasion through producing tissue remodeling molecules, including MMP-2, 9, TNF-α, CXCL10, and IL-1β.Protects cancer cells from cytotoxic effects of radiotherapy and anticancer agents." (PMID 35096289, 2021). "Sponging the miR-140-3p circSMARCC1 prevents the inhibition of metalloproteinases MMP-2 and MMP-9, enhancing cancer cell metastasis activity." (PMID 34298612, 2021). "Other more specific MMPIs, such as tanomastat, a small molecule inhibitor of MMP-2, -3, -8, -9, and -13, prinomastat, which inhibits MMP-2, -3, -9, -13, and -14, and rebimastat, an inhibitor of MMP-1, -2, -3, -8, -9, -13, and -14, were then tested, in cancers." (PMID 34912809, 2021).
cancer (continued). "MMP2 and MMP9 belong to the metzincin superfamily and contribute to the pathogenesis of cancer cell invasion." (PMID 34484336, 2021). "The protein expression of MMP-2 and MMP-9 in cancer tissues was higher than that in pericarcinoma tissues." (PMID 31882379, 2021). "Among them, MMP-2 and MMP-9 are remarkably up-regulated in malignant tumors and contribute to cancer invasion." (PMID 33718164, 2021). "The expression of MMP-2 and MMP-9 was significantly increased in patients with malignant tumors, more importantly, MMP-2 and MMP-9 are essential in in NSCLC invasion and metastasis." (PMID 34895234, 2021). "As two of the most widely studied matrix metalloproteinases (MMP), MMP-2 and MMP-9 play important roles in developmental biology and act as cancer biomarkers." (PMID 34654351, 2021). "Particularly MMP-2 and MMP-9 are important factors of basal membrane degradation and the matter of interest in cancer research." (PMID 34684168, 2021). "MMP-2 (gelatinase-A), and MMP-9 (gelatinase-B) are involved in proteolytic digestion of the extracellular matrix (ECM) for cancer invasion and metastasis." (PMID 34830320, 2021). "Knockdown of Kindlin-2 has been reported to lead to a significant reduction in the invasive properties of cancer cells through nuclear factor kappa B (NF-κB)-dependent upregulation of the expression of matrix metallopeptidase (MMP)-9 and MMP-2." (PMID 34338144, 2021). "Especially, MMP2 and MMP9 are of particular interest for their role in the development and progression of early cancer." (PMID 34006286, 2021). "The serum concentrations of MMP-2 and MMP-9 differ significantly regarding age, presence of microcalcification, irregular shape, diameter or number of cancer foci, and other clinicopathological features mentioned earlier." (PMID 34684168, 2021). "Whereas the most relevant MMPs in this invasive process are MMP-2 and MMP-9, SNAIL was found to induce MMP-9 expression, and EMT was found to be necessary for intravasation of lymph vessels in GBM and other cancers." (PMID 34884812, 2021). "MMP-2 and MMP-9 are found in OvCa patient ascites and aid cancer cell invasion through type IV collagen degradation." (PMID 33810259, 2021). "MMP-2, -9, and -14 TIMP-1 and -2 have been seen to be altered in cell proliferation, invasion, and metastasis in multiple types of cancers." (PMID 34912809, 2021). "In this article, we concentrated on MMP-2 and MMP-9, due to their high expression reporting by various cancers investigations including CRC." (PMID 34337054, 2021). "Type I collagenases such as MMP-2 and MMP-9 participate in cancer growth and invasion by degrading extracellular matrix (ECM)." (PMID 34400947, 2021). "They express cancer stem cell markers, such as CD34, MMP2, nestin, and SOX2, as well as the astro-neuronal lineage markers GALC, TUBB3 (CD56), and OLIG2." (PMID 34638987, 2021). "At the same time, the expression of MMP2, MMP7, and MMP9 (factors in the matrix metalloproteinases family and involved in the invasion of cancers) was detected in the control cells and HCT116-Id4 cells." (PMID 33936204, 2021). "MMP-2 and MMP-9, which contribute to cell migration and invasion, have been found upregulated during EMT in cancer cells." (PMID 34743754, 2021). "To examine more precisely, we compared the expression level of matrix metalloproteinase-2 (MMP-2), which plays crucial role in cancer invasion." (PMID 34112111, 2021). "lncRNA-BX111887 upregulation contributes to the hypoxia-induced EMT of cancer cells by regulating expression of ZEB1 and its downstream genes E-cadherin and MMP2." (PMID 33407675, 2021).